ATM (ATM serine/threonine kinase)
Diseases named in the same sentence as ATM in open-access papers (continued):
Sharing a sentence is not in itself a finding about the gene and the disease.
cancer (continued). "These cancer types have previously been reported in association with ATM gene variants and are considered to have therapeutic implications as well." (PMID 37277882, 2023). "The ATM mutational status and variant allele frequency was confirmed from Cancer Cell Line Encyclopedia data (RRID:SCR_014555; cbioportal.org) and Cell Model Passports (cellmodelpassports.sanger.ac.uk)." (PMID 37663435, 2023). "We showed sensitivity of the cancer cells to ZL-2201 with ATM deficiency; however, the synergy of ZL-2201 with topoisomerase II inhibitors was not ATM dependent." (PMID 37663435, 2023). "Loss of ATM results in a greater risk of developing tumors; therefore, this can be used as an important observational risk factor in cancer progression." (PMID 37674118, 2023). "Individuals who are heterozygous carriers of pathogenic germline variants in ATM are at increased risk of developing several types of cancer." (PMID 38201513, 2023). "A theoretical interest in PARP inhibition in ATM-mutated cancers stems from the involvement of the kinase in the same HR repair pathway as BRCA1 and BRCA2." (PMID 36975505, 2023). "We then calculated the prevalence of germline ATM pathogenic variants among individuals diagnosed with an atypical ATM cancer who tested positive for hereditary cancer predisposition." (PMID 36865800, 2023). "People with variant A‐T have some residual ATM function and consequently a milder clinical phenotype with later age of onset, a slower rate of disease progression and a lower risk of developing cancer in childhood." (PMID 37264737, 2023). "Germinal mutations in ATM produce Ataxia-telangiectasia, an autosomal recessive neurodegenerative disorder with an increased risk of developing cancer (40%), particularly leukemias and lymphomas." (PMID 36672401, 2023). "Many preclinical studies have validated that cancer cells with ATM signaling defects are susceptible to ATR inhibition after being treated with DNA-damaging drugs." (PMID 37298997, 2023). "Mutations, including allelic deletions in the ATM tumour suppressor gene, are common in all cancers." (PMID 37020276, 2023). "The risk of cancer among individuals heterozygous for ATM pathogenic variants has since been demonstrated for a broader range of malignancies." (PMID 36865800, 2023). "The third case with a family history of cancer had a heterozygous synonymous pathogenic variant (c.7788G>A) in the ATM gene found by WES analysis." (PMID 38327652, 2023). "In conclusion, we identified two novel pathogenic variants in one patient with AT disease and two other pathogenic variants in the ATM gene in two families with cancer from the Iranian Azari Turkish population." (PMID 38327652, 2023). "A delayed RIANS caused by the sequestration of ATM monomers in the cytoplasm via overexpressed cytoplasmic ATM substrates (called X-proteins) provides moderate radiosensitivity associated with cancer proneness or accelerated aging." (PMID 37443782, 2023). "Our results suggest that DNA replication acts in concert with genome topological states to fine-tune R-loops and thereby maintain genome integrity, revealing a likely conserved regulatory mechanism of TOP1i resistance in chemotherapy for ATM-deficient cancers." (PMID 38012183, 2023). "For example, PARP and ATR inhibition increases genomic instability and cell death in ATM-deficient cancer cells." (PMID 36794257, 2023). "Our findings will be significant to researchers and physicians in the field of precision medicine and suggest a novel therapeutic component for treating high-risk NB patients showing ATM zygosity and aggressive cancer progression." (PMID 37020276, 2023).
cancer (continued). "Sensitivity of human ATM-mutated cells from various cancers to combinations of PARP inhibitors and ATR inhibitors has been observed." (PMID 36975505, 2023). "Present observations exhibited a robust association between ATM methylation and organ invasion, depth invasion (≥8 mm), well-differentiated cancer, and >5 sampled nodes." (PMID 37560303, 2023). "Accordingly, patients with homozygous germline ATM mutations can develop severe toxicity with radiation for cancer treatment." (PMID 37206490, 2023). "Twenty-five of these patients had a personal or family history of cancer that is consistent with the currently described spectrum of ATM-associated malignancies." (PMID 36865800, 2023). "The association of ATM with cancer susceptibility has directly influenced clinical practice, from the creation of gene panels for molecular testing to cancer surveillance guidance and treatment recommendations." (PMID 36865800, 2023). "Studies in the literature on relatives with heterozygous ATM gene mutations have shown an approximately 2-3 times increased risk of cancer in women and a 5-9 times increased risk of BC." (PMID 38021491, 2023). "In NSCLC cell lines, AZD6738 boosted gemcitabine and cisplatin cytotoxicity while also increasing cisplatin anti-cancer properties in ATM-deficient NSCLC cells." (PMID 37062547, 2023). "The combined data from these studies were then used to estimate the prevalence of germline ATM pathogenic variants in these cancers, which ranged between 0.45% and 2.2%." (PMID 36865800, 2023). "Analysis of ATM mutation frequency in The Cancer Genome Atlas cohort indicated that ATM is mutated in approximately 5% of all cancers." (PMID 37627223, 2023). "Unfortunately, the feasibility of case-control studies is limited by the rarity of many of these cancers, as well as the low penetrance of ATM in association with these atypical cancers." (PMID 36865800, 2023). "Regarding the mutation hotspots and mutation types in cancer, most of the truncating mutations of ATM, ATR, CHEK1, and CHEK2 are considered to be, at least, likely pathogenic." (PMID 37373360, 2023). "In ATM-deficient cancer cells, the ATR inhibitor ceralasertib combined with the DNA crosslinker, PBD SG-3199, activated dendritic cells in a STING-IFN-dependent manner, externally fortifying tumor immunogenicity." (PMID 37109350, 2023). "Cancer susceptibility is one of the characteristics of A-T and is caused by loss of ATM activity because of homozygous loss-of-function variants in the ATM gene." (PMID 35008949, 2022). "Several studies demonstrated that DNA damage promotes chemoresistance and drives epithelial-to-mesenchymal transition (EMT) via the activation of altered ataxia telangiectasia mutated (ATM) dependent signaling in several cancer settings, including NSCLC." (PMID 35626121, 2022). "A loss of the checkpoint kinase ataxia telangiectasia mutated (ATM) leads to impairments in the DNA damage response, and in humans causes cerebellar neurodegeneration, and an increased risk of cancer." (PMID 35200138, 2022). "Cancer-associated germline variations, namely ATM p.Lys468fs and PALB2 c.2835-1G>C, were detected in 2 of 56 patients with solid pseudopapillary tumors (3.6%)." (PMID 35171259, 2022). "Nowadays, novel therapies have been developed to selectively target patients with ATM-deficient cancers." (PMID 35723313, 2022). "For example, the loss of Ataxia Telangiectasia-mutated (ATM) frequently observed in a variety of cancers is likely due to a driver mutation occurring at an early stage during lung carcinogenesis." (PMID 35251998, 2022). "Since then, other malignancies, such as pancreatic cancer, have been linked to ATM through studies conducted on cancer cohorts." (PMID 36555667, 2022).
cancer (continued). "Deficiency of ATM-mediated signalling reactions causes sensitisation of cells to radiation, which has sparked interest in ATM as a therapeutic target for cancer treatment." (PMID 36106115, 2022). "In another study, inhibition of Ataxia telangiectasia mutated (ATM) enhanced cancer immunotherapy by promoting mitochondrial DNA leakage and cGAS/STING activation." (PMID 36221123, 2022). "The most observed variants in PDAC include BRCA1/2 (breast cancer gene 1/2) and ATM (ataxia telangiectasia mutated)." (PMID 35205732, 2022). "Blocking ataxia telangiectasia mutated (ATM), a crucial player in DNA repair responses, has been proposed as a promising strategy in anti-cancer therapy." (PMID 35795059, 2022). "The germline variants R3008H and R805X in ATM as well as the substitution P1275L in CDK12 correlated with cancer familiarity." (PMID 35347810, 2022). "EZH2 is an epigenetic silencer of the polycomb repressor complex 2; a negative regulator of DNA damage-related proteins of ATM involved in the X-ray-induced DNA damage; and has been associated with the prognosis of several cancer entities." (PMID 35160302, 2022). "According to TCGA pan cancer studies, ATM mutations are found in approximately 5.3% of all cancers and are most common in uterine corpus endometrial cancer (19.1%) followed by bladder urothelial cancer (13.4%) and colorectal adenocarcinoma (13.1%)." (PMID 35008949, 2022). "For example, ATM pathogenic germline variants are increasingly found to be associated with a wider cancer spectrum than previously known, and cancer risk management programs for ATM carriers have been proposed." (PMID 35326540, 2022). "Combining PARP and ATR inhibitors synergistically promoted anti-tumor efficacy against ATM-deficient cancer cells in xenograft and PDX mouse models." (PMID 35008949, 2022). "In murine and human cancer cell lines, ATM deficiency induces ISG expression and tumor infiltration of immune cells in a cGAS/STING-dependent manner." (PMID 36276148, 2022). "This strategy is emerging in a clinical trial using Ceralasertib, with preliminary results in a small multi-cancer cohort of patients with ATM-mutated tumors showing early promise." (PMID 35205643, 2022). "Recent results from phase I clinical studies have demonstrated durable anti-tumor activity of ATR inhibitors in advanced cancers with either deleterious ATM mutations or loss of ATM protein expression." (PMID 35954206, 2022). "A series of preclinical research studies have also indicated that cancer cell with ATM deficiency was less sensitive to PARPi than that with BRCA2 mutations." (PMID 36253861, 2022). "Recently, multiple studies have documented associations between increased risk of several types of cancers and heterozygous ATM germline pathogenic variants (PVs)." (PMID 35008949, 2022). "For both A-T patients and carriers of ATM heterozygous germline variants, high risks for cancer have been reported." (PMID 35008949, 2022). "The clinical efficacy was evident in other cancer types due to BRCA1/2 or other deleterious mutations in the HR pathway (such as ATM), specifically pancreatic and prostate cancers." (PMID 36358724, 2022). "Core (BRCA1/2, PALB2), and any HRR mutations (BRCA1/2, PALB2, CHEK2, FANCA, ATM) occurred in 13 (10.3%) and 22 (17.5%) cancers, respectively." (PMID 36124727, 2022). "The role of THs in cancer is further complicated by the fact that THs can promote senescence through the activation of ataxia-telangiectasia mutated (ATM)/adenosine monophosphate-activated protein kinase (PRKAA) proteins." (PMID 35743483, 2022).
cancer (continued). "Among these, the dual DNA‐PK/TOR kinase inhibitor CC‐115, which targets ATM‐deficient cancer cells in vitro showed promising response in phase I clinical trials." (PMID 35107878, 2022). "Women who carry an ATM mutation have a 20–30% lifetime risk to develop breast cancer, and carriers also have a possible but as yet undefined risk for other cancers, such as prostate, pancreatic and colon cancer." (PMID 35732815, 2022). "While ATM has several tumor suppressing functions, ATM-induced signaling can cause tumor progression via the αvβ3 integrin pathway in some cancers." (PMID 35872888, 2022). "Research has shown that some cancers have ATM gene mutations which render them more sensitive to anticancer therapy, and that this can be exploited by using targeted therapies which induce a synthetic lethal status." (PMID 35150356, 2022). "It appears that the mutated proteins that cause the major cancer and radiosensitivity syndromes are all ATM phosphorylation substrates, and they generally localize in the cytoplasm when mutated." (PMID 36551628, 2022). "Heterozygous carriers of ATM pathogenic variants are in general asymptomatic, but they have a reduced life expectancy because of mortality from cancer (mainly breast and digestive tract malignancy) and ischemic heart disease." (PMID 35454905, 2022). "For example, some specific mutations of XPD were shown to sequestrate ATM in the cytoplasm after exposure to IR and lead to cancer proneness and radiosensitivity." (PMID 36551628, 2022). "Further cancer risks that are associated with these MBCG are pancreatic cancer for ATM, CHECK2, and PALB2, and colon and prostate cancer for CHEK2." (PMID 35329227, 2022). "Defects in ATM give rise to ataxia-telangiectasia (A-T), a multisystem disorder that is characterized by a predisposition to cancer and progressive neurodegeneration." (PMID 35200138, 2022). "In vitro and in vivo experiments have also confirmed that ATM loss increases sensitivity to ATRis in various types of cancer." (PMID 36497387, 2022). "Our analysis has also revealed that R337C/H are the most common cancer-related missense mutations in the ATM gene, accounting together for 7.94% of all ATM variant carriers." (PMID 35158934, 2022). "Ataxia-telangiectasia mutated (ATM) targeted agents are among the DDR inhibitors currently undergoing evaluation for cancer treatment." (PMID 36309653, 2022). "In vitro studies have shown increased radiosensitivity after pharmacologic inhibition of ATM and in cancer harboring ATM mutations." (PMID 36552003, 2022). "Although ATM is frequently mutated across cancer types, functional ATM deficiency due to hypermethylation of its promoter region is more common." (PMID 36420962, 2022). "In a meta-analysis of ATM variants, a later study found strong evidence that a subset of rare evolutionary unlikely missense variants confer increased cancer risk." (PMID 35039564, 2022). "ATM germline mutation increases the likelihood of PC development, and ATM mutation or protein loss are enriched in high-grade cancer." (PMID 36362213, 2022). "The ATM gene is a pathogenic mutation gene on chromosome 11q22.3, which is one of the frequently mutated genes in cancer." (PMID 35521981, 2022). "Mice, rats, and flies with mutations of ATM have shown A-T characteristics, including neural degeneration, meiotic defects, radiation hypersensitivity, immunological abnormalities, and cancer." (PMID 35203601, 2022). "PV were detected in 13 cancer predisposition genes including ATM (n=4), BLM (n=1), BRCA1 (n=1), BRCA2 (n=7), BRIP1 (n=1), CDKN2A (n=1), CHEK2 (n=9), FANCC (n=1), MUTYH (n=10), NBN (n=1), PALB2 (n=1), RAD51D (n=1) and STK11 (n=1)." (PMID 36091166, 2022).
cancer (continued). "Based on this rationale, several DNA damage response inhibitors are currently being tested in ATM-deficient cancers." (PMID 35008949, 2022). "DNA-PKi can be used as a single agent in some cancers with ATM deficiency by inducing synthetic lethality." (PMID 36276148, 2022). "A variety of ATM-deficient cancer cell lines showed sensitivity to PARP inhibitors, including CRC cell lines." (PMID 34201502, 2021). "The global importance of such rare variants in tumorigenesis has been addressed by pan-cancer analysis, revealing significant enrichments for protein truncating variants in genes such as ATM, BRCA1/2, BRIP1, and MSH6." (PMID 33809641, 2021). "Heterozygous germline ATM mutation carriers had an increased risk of developing cancer of the breast, pancreas, and other organs." (PMID 34068084, 2021). "Not surprisingly, the pro-oncogenic role of RAD52 is especially pronounced in cancer cells that are deficient in DDR pathways, like ATM-deficient cancers." (PMID 34887904, 2021). "Full genome sequence analysis of cancer cells, especially of those resistant to chemotherapy or radiation, discovered the presence of many different ATM somatic and germinal mutations, especially in the PI3K conserved domain where kinase domain is located." (PMID 34771661, 2021). "Many human cancers, reported on The Cancer Genome Atlas (TCGA) database, were ATM mutated and from the analysis of these mutations, Yamamoto and colleagues revealed that 72% of those are missense mutations that are highly enriched in the kinase domain." (PMID 34771661, 2021). "Meanwhile, the ATM inhibitor KU-60019 was specifically toxic in PTEN-deficient cancer cells and tumor xenografts compared to wild-type cells." (PMID 34930377, 2021). "Frequently detected genetic alterations (>5% in >5 samples across all studies) in GBC for which targeted therapies are available in other cancer types included mutations in ATM, ERBB2, and PIK3CA, and ERBB2 amplifications." (PMID 34771420, 2021). "Another international workshop for the ATM and cancer risk has begun to collect population-based worldwide data of germline variants in ATM associated with HBOC." (PMID 35008774, 2021). "Our findings provide insights into the potential functional impact of numerous ATM/ATR mutations found in cancer." (PMID 33742106, 2021). "Germline ATM mutation likely contributes to Ataxia Telangiectasia (A‐T), a neural degeneration disorder characterized by increased predisposition to cancer." (PMID 34977872, 2021). "Previous studies have established enhanced efficacy with the combination of AZD6738 and olaparib in BRCA- mutant and ATM-deficient cancer models." (PMID 34027408, 2021). "In contrast, BRAF and ATM are both well-established cancer driver genes, and these two kinase-containing genes were found mutated in 8 and 5% of cancers, respectively." (PMID 34645806, 2021). "While the ATM V2424G variant was one of the forms associated with an increased risk of cancer, the ATM D1853V missense variant has the least association with BC risk." (PMID 34068084, 2021). "Recent studies have also shown their potential role in the treatment of other ATM-deficient cancers, and clinical trials on patients with potentially actionable ATM-deficient cancers are ongoing." (PMID 34262154, 2021). "Accordingly, RBM6-deficient cancer cells are vulnerable to ATM and PARP inhibition and show remarkable sensitivity to cisplatin." (PMID 34718714, 2021). "According to the network, POLD1 was observed to interact with ATM, which is a DNA damage response gene commonly mutated in cancer." (PMID 33747905, 2021).